PCDHA10 (protocadherin alpha 10)
Description:
Potential calcium-dependent cell-adhesion protein. May be involved in the establishment and maintenance of specific neuronal connections in the brain.
Synonyms: CNRS8; CNR8; CRNR8; CNRN8; PCDH-ALPHA10
Tractability: Antibody: UniProt places it where antibodies can reach, with high confidence; its Gene Ontology location is reachable by antibodies, with high confidence; UniProt predicts a signal peptide or a membrane-spanning region.
Gene: Protein-coding gene on chromosome 5 (140,855,883 to 141,012,347, forward strand). Ensembl gene ENSG00000250120.
Subcellular location: Cell membrane; Secreted (Isoform 2)
Gene Ontology:
Molecular function: cell adhesion molecule binding; calcium ion binding
Biological process: cell adhesion; nervous system development; homophilic cell-cell adhesion
Cellular component: plasma membrane; cell-cell contact zone; extracellular region; membrane
Genetic constraint (gnomAD): Loss-of-function variants: 45 observed, 63.27 expected, observed/expected ratio (o/e) 0.71, 90% interval 0.56 to 0.91. The upper end of that interval is the gene's LOEUF score, 0.91, which puts it in group 3 of 6, group 1 being the genes least tolerant of losing a copy. Missense variants: 1,278 observed, 1,288.2 expected, observed/expected ratio (o/e) 0.99, 90% interval 0.95 to 1.04. Synonymous variants: 602 observed, 578.31 expected, observed/expected ratio (o/e) 1.04, 90% interval 0.97 to 1.11.
Homologues: Orthologues: mouse Pcdha9 (83% identical). Paralogues in human: PCDHA12 (82% identical), PCDHA6 (82% identical), PCDHA8 (81% identical), PCDHA4 (81% identical), PCDHA9 (81% identical), PCDHA3 (81% identical), PCDHA11 (81% identical), PCDHA7 (81% identical), PCDHA13 (80% identical), PCDHA5 (80% identical), PCDHA2 (80% identical), PCDHA1 (79% identical), and 49 more.
Diseases named in the same sentence as PCDHA10 in open-access papers:
PCDHA10 is named in the same sentence as 5 diseases in open-access papers, as found by Europe PMC text mining. Sharing a sentence is not in itself a finding about the gene and the disease. The quoted sentences say what the papers report.
breast carcinoma (2 papers, 2022 to 2025). "Through model interpretation and biological experimental validation, we identified three novel breast cancer genes—PCDHA10, PRICKLE2, and PRTG—demonstrating their inhibitory effects on cell proliferation and migration in breast cancer cell lines." (PMID 40581983, 2025). "As an example of TET2 CD–mediated gene activation, a subset of TSS-CGIs from the breast cancer-methylated PDCHA locus selectively gained H3K4me3 in TET2 CD cells in correlation with the activation of the associated genes as shown for PCDHA4, PCDHA3, PCDHA9, and PCDHA10." (PMID 35351824, 2022). "Using cfMethylPre, we identified and validated three novel genes—PCDHA10, PRICKLE2, and PRTG—that exhibit inhibitory effects on breast cancer cell proliferation and migration, highlighting its potential in precision oncology." (PMID 40581983, 2025). "Using this capability, we detected and validated three genes—PCDHA10, PRICKLE2, and PRTG—demonstrating their inhibiting effects on cancer cell growth and migration in breast cancer cell lines." (PMID 40581983, 2025). "Furthermore, its interpretability enables the identification of critical cancer-associated genes, with experimental validation uncovering three novel genes—PCDHA10, PRICKLE2, and PRTG—that exhibit inhibitory effects on breast cancer cell proliferation and migration." (PMID 40581983, 2025).
depression (1 paper, 2024). "The overlapping eQTL genes between AD and depression (SRA1, MICA, PCDHA8, PCDHA10, PCDHA7, and PCDHA13), were not yet associated with these disorders through proximity analysis nor have an established role in these diseases as of yet." (PMID 38862462, 2024).
PCDHA10 also shares sentences with these, for which no sentence is quoted: cancer (2 papers); Alzheimer disease (1); melanoma (1).